PIEZO1 (piezo type mechanosensitive ion channel component 1 (Er blood group))
Diseases named in the same sentence as PIEZO1 in open-access papers (continued):
Sharing a sentence is not in itself a finding about the gene and the disease.
Insulin resistance (8 papers, 2019 to 2025). Increased resistance towards insulin, that is, diminished effectiveness of insulin in reducing blood glucose levels. "Deletion of Piezo1 specifically in adipocytes reduces perigonadal fat mass and causes adipose inflammation, insulin resistance, and hepatic steatosis." (PMID 31263454, 2019). "We suggest that the reduced size of the adipocytes together with the improvements in insulin resistance and inflammation associated to weight loss achieved by surgery or caloric restriction may be the responsible for the reduction in Piezo1 expression levels." (PMID 39707172, 2024). "When challenged with a HFD, adipose-Piezo1−/− mice showed exacerbated insulin resistance as evidenced by significantly increased glucose levels in GTT and ITT, and elevated insulin and HOMA-IR index." (PMID 31263454, 2019). "As a result, impaired Piezo2–Piezo2 crosstalk-induced autonomic dysregulation and impaired Piezo2–Piezo1 crosstalk could prevail, resulting in insulin resistance, because Piezo1 has a role in glucose-induced insulin secretion." (PMID 40076941, 2025). "Although the precise mechanisms linking PIEZO1 and insulin resistance are not fully understood, adipocyte hypertrophy may also be an important mediator." (PMID 39707172, 2024). "Consistent with this, Ad-Piezo1-KO mice that received HFD exhibited a significantly reduced glucose tolerance, a modest increase in insulin resistance and increased insulin plasma levels." (PMID 32385276, 2020). "Injection of GLP-1 analog Exendin-4 (Ex-4) decreased the body weight and improved both glucose tolerance and insulin resistance in control and Piezo1 IntL-CKO mice, while endogenous synthesis of GLP-1 was not changed by Ex-4 injection in Piezo1 IntL-CKO mice." (PMID 39509292, 2024). "Irrespective of the timing, Piezo1 gene inactivation increases inflammation, glucose intolerance, and insulin resistance in DIO mice." (PMID 36749637, 2023).
liver cancer (8 papers, 2022 to 2026). An epithelial or non-epithelial malignant neoplasm that arises from the liver. "Furthermore, Piezo1 may be associated with various liver diseases, including hepatic iron overload, hepatitis, liver fibrosis, cirrhosis, and liver cancer." (PMID 41017814, 2025). "In various tumor types—including gliomas, gastric, breast, and liver cancers—Piezo1 is highly expressed." (PMID 40821847, 2025). "In chemoresistant tumor models—including pancreatic and liver cancers—the activation of the Piezo1–MDSC axis is a major contributor to immunotherapy failure." (PMID 40821847, 2025). "By reducing Piezo1 expression and localizing Yes-associated protein (YAP) to the nucleus, a previous study has demonstrated that tumor growth in HepG2-derived liver cancer can be inhibited." (PMID 41017814, 2025). "Correspondingly, in Piezo1-knockout mice, the growth and development of liver cancer tumors are prevented." (PMID 36615408, 2022). "In liver diseases, targeting Piezo1 could offer a promising therapeutic strategy by regulating YAP/TAZ signaling activity to mitigate liver fibrosis or inhibit liver cancer progression." (PMID 41017814, 2025). "Piezo1 may act as a regulator of numerous signaling pathways and is involved in diverse forms of liver cancer through various pathways." (PMID 41017814, 2025). "There is increasing evidence suggesting Piezo1 as a potential drug target in liver cancer." (PMID 41017814, 2025). "Furthermore, in a high-stiffness Sprague Dawley (SD) rat orthotopic liver cancer model, a positive feedback regulatory loop involving stiff matrix/integrin β1/miR-625-5p/Piezo1 and COL1/stiffer matrix mediates the upregulation of Piezo1 expression by matrix stiffness." (PMID 41017814, 2025). "Thus, targeting Piezo1 may offer promising therapeutic avenues for treating liver cancer." (PMID 41017814, 2025). "Interestingly, PIEZO1 mRNA expression was mainly detected in SNU-761, Hep 3B2.1-7, and HuH-1 liver cancer cell lines." (PMID 40977743, 2025). "A market opportunity study update confirms that Piezo1 is highly expressed in HepG2 cell lines, and the absence of Piezo1 promotes the proliferation, migration, and apoptosis of liver cancer cells." (PMID 36615408, 2022).
migraine (8 papers, 2020 to 2025). "This long-lasting labelling can be used to monitor the ongoing and previous activation of Piezo1 channels in the trigeminal nociceptive system, which is implicated in migraine pain." (PMID 36675204, 2023). "Our studies indicated that both Piezo1 and Piezo2 channels are expressed in trigeminal sensory neurons, which innervate head and face tissues and implicated in generation of migraine pain." (PMID 31973098, 2020). "In migraine models, PIEZO1 and PIEZO2 were found to be co-expressed in trigeminal afferents, where they contribute to the mechanosensory amplification of vascular pulsation-induced pain." (PMID 40863236, 2025). "It has been proposed that mechanosensitive Piezo1 channels trigger migraine pain in trigeminal nociceptive neurons, but the mechanosensitivity of satellite glial cells (SGCs) supporting neuronal sensitization has not been tested before." (PMID 36675204, 2023). "In the current review, we will focus on the potential role of the recently discovered mechanosensitive Piezo1/2 channels in the nociceptive signaling in migraine." (PMID 31973098, 2020). "Therefore, the identification of currently and previously activated Piezo1 channels would unleash molecular mechanisms of the inflammatory and pro-nociceptive triggers that contribute to the onset of migraine pain." (PMID 36675204, 2023). "This discovery could help in the monitoring of both previous and ongoing activity of Piezo1 channels in the trigeminovascular system, the origin site of headaches in migraines." (PMID 36675204, 2023). "As the activation of these channels in meningeal afferents has previously been proposed to play a role in migraines, it is tempting to speculate that mechanisms converging on Piezo1 and TRPV1 channels play a role in various types of headaches." (PMID 36293444, 2022). "Moreover, the co-activation of Piezo1 and TRPV1 nociceptive channels after stroke raises the interesting issue of potential functional interactions between these two signaling pathways, likely implicated in migraines." (PMID 36293444, 2022). "In migraine models, PIEZO2 contributes to trigeminal hypersensitivity, while PIEZO1 regulates dural endothelial permeability, offering new entry points for treating neurovascular headache syndromes." (PMID 40863236, 2025). "It is still unclear whether glial cells even express mechanosensitive Piezo1 channels and whether these receptors contribute to their crosstalk with neurons, leading to neuroinflammation and neuronal sensitization, which are contributing factors to migraine pain." (PMID 36675204, 2023). "In addition, we assessed the relative contribution of mechanosensitive TRPM3 channels and that of mechanosensitive Piezo1 channels and transient receptor potential vanilloid 1 (TRPV1) channels to nociceptive firing relevant to migraine in both sexes." (PMID 35012445, 2022). "As Piezo1 and mechanosensation have many additional functions besides migraine generation, the higher activity of Piezo1 in DRG than in TG neurons, is not surprising." (PMID 35163293, 2022). "However, unlike in our study, the interaction in migraine occurs in the periphery with highly vascularized dura rather than within the sensory ganglion; the time course is much slower than the clustered firing observed in DRG neurons; and Piezo1 rather than Piezo2 is implicated." (PMID 40154477, 2025).
Arrhythmia (7 papers, 2021 to 2026). Any cardiac rhythm other than the normal sinus rhythm. "Although no data are available at present regarding the prevalence of cardiac arrhythmias in patients suffering from this condition, mice have been engineered to contain a specific gain-of-function PIEZO1 mutation found in these patients." (PMID 37047693, 2023). "However, in human patients suffering from cardiac arrhythmias, it is unlikely that this condition is caused by an overexpression of PIEZO1, specifically in cardiomyocytes." (PMID 37047693, 2023). "Based on this, we believe it is possible that PIEZO1 genetic variants with gain-of-function properties could be responsible for cardiac arrhythmias in humans." (PMID 37047693, 2023). "A more logical scenario is that certain genetic variants in PIEZO1 could lead to a gain of function and subsequent cardiac arrhythmia." (PMID 37047693, 2023). "This also raises the possibility that PIEZO1 gain of function mutations could be linked to heritable cardiac arrhythmias in humans." (PMID 37047693, 2023). "To confirm that prolonged Piezo1 activation results in cardiac arrhythmia, we adopted an optical mapping approach combined with a voltage-sensitive dye to assess the spatiotemporal dynamics of excitable events in the whole heart in vivo." (PMID 37047693, 2023). "In summary, our data encourage PIEZO1 genetic sequence analysis for patients suffering from hereditary cardiac arrhythmias." (PMID 37047693, 2023). "Here, we demonstrate, using a combination of pharmacology and an array of different cardiac analyses, that prolonged Piezo1 activation results in significant cardiac arrhythmias in zebrafish." (PMID 37047693, 2023). "Taken together, these data indicate that Yoda1 treatment affects heart performance and indicates that prolonged Piezo1 activation results in cardiac arrhythmia." (PMID 37047693, 2023). "Here, we have shown that Yoda1-induced PIEZO1 activation results in cardiac arrhythmias in zebrafish larvae." (PMID 37047693, 2023). "Conversely, cardiac myocyte–specific overexpression of PIEZO1 in nonligated mice reduced the ejection fraction and caused arrhythmia, which suggests that excess cardiac myocyte PIEZO1 alone can drive adverse cardiac events." (PMID 40721314, 2025). "Recent evidence indicates that PIEZO1 plays a significant role in cardiomyocyte Ca2+ handling in response to mechanical stretch, and could be an important factor in the generation of cardiac arrhythmias." (PMID 37047693, 2023). "We speculate that Yoda1 treatment could be mimicking the effects of pathological situations such as atrial stretch and increased arterial blood pressure, which can activate PIEZO1 and result in similar cardiac arrhythmias." (PMID 37047693, 2023). "Murine studies revealed that cardiac-specific Piezo1 deletion led to impaired heart pump function, whereas cardiac-specific overexpression of Piezo1 led to severe HF and arrhythmia; together indicating an essential role for myocyte Piezo1 in maintaining normal cardiac function." (PMID 33922466, 2021). "Furthermore, chemically prolonging PIEZO1 activation in zebrafish results in cardiac arrhythmias." (PMID 37047693, 2023).
Cognitive impairment (7 papers, 2023 to 2025). Abnormal cognition is characterized by deficits in thinking, reasoning, or remembering. "The deficiency of astrocytic Piezo1 in the hippocampus leads to a decrease in neurogenesis via an ATP‐dependent downstream pathway, resulting in cognitive impairment." (PMID 38923822, 2024). "In the present study, we found that both PIEZO1 and calpain inhibition decreased TrkB degradation and maintained memory performance similar to EE, suggesting that EE could counteract the cognitive impairment caused by sleep deprivation by inhibiting PIEZO1/calpain signaling." (PMID 37485782, 2024). "Conversely, the inhibition of PIEZO1 or calpain ameliorated cognitive impairment and autophagy was similarly inhibited." (PMID 37485782, 2024). "Modulation of basal forebrain PIEZO1 signaling by pharmacological or non‐pharmacological means may be an effective strategy to counteract sleep deprivation‐induced cognitive impairment." (PMID 37485782, 2024). "Our results suggested that LIPUS could improve cognitive impairment and increase hippocampal synaptogenesis through the Piezo1-mediated Calpain1/ Erk pathway." (PMID 37190622, 2023). "Further studies have demonstrated that inhibition of Piezo1/Ca2+/calpain signaling could attenuate neuronal apoptosis and improve cognitive impairment." (PMID 37190622, 2023). "Pharmacological inhibition of Piezo1 during chronic cerebral hypoperfusion also improved BBB disruption and cognitive impairment, further supporting a role for Piezo1 as an important mechanosensor of capillary perfusion." (PMID 40769996, 2025). "Collectively, these behavioral findings indicate that TMAS can ameliorate cognitive impairment in 5xFAD mice to a greater extent than TUS and that Piezo1 plays a key role in TMAS-induced learning and memory formation." (PMID 37223482, 2023).
colitis (7 papers, 2022 to 2025). Inflammation of the colon. "Piezo1-deficient mice were less susceptible to dextran sulfate sodium (DSS)-induced colitis, whereas Yoda1 treatment aggravated colitis." (PMID 36119083, 2022). "Furthermore, conditionally Piezo1-deficient mice were less susceptible to dextran sulfate sodium (DSS)-induced colitis, whereas Yoda1 treatment aggravated disease progression." (PMID 36119083, 2022). "Loss of TFF3, AGR2 was linked to impaired mucus and increased susceptibility to dextran sodium sulfate-induced colitis., GC Piezo1-/- mice exhibited decreased expression of Mucin2, TFF3, AGR2, and thinner mucus layer, which was consistent with the decreased GC numbers." (PMID 36425784, 2022). "For instance, specific deletion of mouse Piezo1 in the intestinal epithelium significantly disrupted gut peristalsis, impeded experimental colitis, and suppressed serum 5-HT levels." (PMID 40495117, 2025). "For instance, research have demonstrated an upregulation of PIEZO1 activity in myeloid cells during colitis, indicating its extensive involvement in the regulation of inflammation." (PMID 40495117, 2025). "In patients with dextran sulfate sodium (DSS)‐induced colitis, Piezo1 is activated by abnormal blood flow." (PMID 39425504, 2024). "In a dextran sulfate sodium (DSS)‐induced colitis murine model, Piezo1 knockout in macrophages reduced diarrhea and increased survival rates, while the Piezo1 agonist Yoda1 exacerbated colon inflammation." (PMID 39425504, 2024). "Piezo1 is expressed in colon microvascular endothelial cells and is activated by stimulation like blood flow disorder during colitis." (PMID 37629134, 2023). "Deficiency of Piezo1 in monocytes, macrophages and granulocytes made mice less susceptible to DSS-induced colitis, and treatment with Yoda1, an agonist of Piezo1, exacerbated colitis." (PMID 36467420, 2022). "First, we did not investigate the time course of changes in the gut microbiota and the sensitivity to dextran sodium sulfate-induced colitis in GC Piezo1-/- mice." (PMID 36425784, 2022). "The activated Piezo1 promotes the shift of macrophages metabolism into aerobic glycolysis and increases the secretion of IL-1β, IL-6, TNF-α, while knock-out of Piezo1 inhibits aerobic glycolysis in colon macrophages of colitis induced by dextran sulfate sodium salt." (PMID 37629134, 2023). "Therefore, we aimed to confirm the role of Piezo1 in vivo in a DSS-induced colitis mouse model using transgenic mice." (PMID 36119083, 2022). "In addition, the published scRNA-seq data (GSE138902) showed that Piezo1 was expressed in a substantial part of recruited macrophages during colitis." (PMID 36119083, 2022). "Moreover, Piezo1 deficiency ameliorated DSS-induced colitis by limiting the glycolytic level and cytokine secretion of macrophages in vivo, whereas Yoda1 treatment aggravated DSS-induced colitis." (PMID 36119083, 2022).
diabetes (7 papers, 2022 to 2026). "However, in pathological situations such as diabetes, endothelial cell damage may cause up-regulation of Piezo1 in smooth muscle cells, aiding in blood vessel relaxation." (PMID 38955832, 2024). "When challenged with high-fat diet, Piezo1 IntL-CKO mice exhibited more severe symptoms of diabetes which was mitigated by Ex-4." (PMID 39509292, 2024). "To study the function of Piezo1 in endothelial cells in diabetes, we first analyzed the expression of Piezo1 in induced pluripotent stem cell-derived endothelial cells in diet-induced hyperglycemic obese mice and compared it with healthy mice (GSE54387)." (PMID 38702777, 2024). "A previous study demonstrated that dysregulation of Piezo1 occurs in multiple blood lineages in patients with type 2 diabetes mellitus (T2DM)." (PMID 38955832, 2024). "Moreover, several studies have reported the involvement of Piezo1 in diabetes and high glucose conditions." (PMID 38702777, 2024). "Interestingly, Piezo1 expression is elevated in islets from humans with type 2 diabetes and in the db/db mouse model of diabetes, in which Piezo1 translocates from the plasma membrane to the nucleus." (PMID 37781915, 2023). "Although the significance of Piezo1 in vascular function has been studied, no reports have investigated the involvement of Piezo1 in diabetic vascular dysfunction." (PMID 38955832, 2024). "Research has indicated that deregulation of Piezo1 has been observed in several lineages of individuals diagnosed with type 2 diabetic mellitus (T2DM), which can promote Piezo1 transcription in mature blood cells and specific hematopoietic stem cell clones with high Piezo1 expression for cloning." (PMID 38702777, 2024).
endothelial dysfunction (7 papers, 2023 to 2025). In vascular diseases, endothelial dysfunction is a systemic pathological state of the endothelium (the inner lining of blood vessels) and can be broadly defined as an imbalance between vasodilating and vasoconstricting substances produced by (or acting on) the endothelium. "This review aims to provide a novel perspective on the potential role of PIEZO1 as a promising target for mitigating COVID-19-associated endothelial dysfunction." (PMID 38487535, 2024). "Correspondingly, superoxide production in HG-exposed HUVECs was also increased by treatment with Yoda1; however, it was significantly reduced upon loss of Piezo1 expression, suggesting the involvement of superoxide in Piezo1 activation for regulation of endothelial dysfunction." (PMID 38702777, 2024). "Therefore, we suggested that Piezo1 activation may cause or accompany inflammation, aggravating endothelial dysfunction induced by HG." (PMID 38702777, 2024). "Piezo1 is highly expressed in vascular endothelium and may be activated by vascular shear stress or elevated intravascular pressure, leading to endothelial dysfunction." (PMID 37781915, 2023). "Importantly, Piezo1 activation in LSECs was induced when exposed to high hydrostatic pressure, which was similar to LSEC/endothelial dysfunction in cirrhosis, and subsequently triggered nuclear translation of NF-κB and stimulated AQP1 expression." (PMID 41034523, 2025). "Altogether, these results provide novel evidence linking the regulation of PIEZO1 and MRG by altered blood flow patterns, which may contribute to the endothelial dysfunction observed in pro-inflammatory conditions." (PMID 37891953, 2023). "Other major endothelial ion channels, including Piezo1 and select members of the transient receptor potential (TRP) family of channels (e.g. TRPM2/4) have each been shown to be modulated by saturated FAs in ways that could promote endothelial dysfunction." (PMID 40996861, 2025).